ERBB2 (erb-b2 receptor tyrosine kinase 2)
Diseases named in the same sentence as ERBB2 in open-access papers (continued):
Sharing a sentence is not in itself a finding about the gene and the disease.
breast cancer (continued). "In addition, these ERBB2 mutations are infrequent (<5%) in breast cancer, suggesting a unique molecular feature of EMPD." (PMID 40726246, 2025). "Recent findings from the DESTINY-PanTumor01 study have highlighted the expanding potential of ErbB2-targeted therapies beyond breast cancer, demonstrating that trastuzumab deruxtecan shows significant efficacy across multiple solid tumors with activating ErbB2 mutations." (PMID 39908697, 2025). "For breast carcinoma patients, approximately 20% have copy number amplification of receptor tyrosine-protein kinase erbB-2 (ERBB2) gene, resulting in highly expressed ErbB2 protein, which is associated with increased tumor aggressiveness, relapse, and mortality." (PMID 39786928, 2025). "Regardless of the presence or absence of HER‐2 amplification, deletion, functionally important somatic mutations, and downregulation of the FOXP3 gene were frequently observed in human breast cancer samples and significantly linked with HER‐2/ErbB2 overexpression." (PMID 38827026, 2024). "Furthermore, our study's results demonstrate that 2.5% (3 out of 116) of Taiwanese patients with breast cancer had detectable targetable ERBB2 activating mutations within the kinase domain." (PMID 38895905, 2024). "A phase 2 trial (plasma MATCH trial) of treatment selection with ctDNA mutations in breast cancer showed the efficacy of neratinib for ERBB2 mutations and capivasertib for AKT1 mutations in ctDNA, indicating the usefulness of examining genetic mutations in ctDNA." (PMID 38539518, 2024). "In addition, 23–32% of the human breast cancers characterized by amplification of the ERBB2 gene (the locus encoding the HER2 protein) show co-amplification of the RARα gene (RARA)." (PMID 38360674, 2024). "After successful completion of this regimen, the patient sustained pCR with a small focus of DCIS and no nodal metastases, suggesting the potential benefit of neoadjuvant chemoimmunotherapy in treating a subset of ER+ErbB2- patients with high-risk, basal-type breast cancer." (PMID 39006626, 2024). "In addition, it has also been observed that inhibitory-κB kinase α (IKKα) increases the invasive potential of ErbB2-positive breast cancer cells, which in turn causes ErbB2 to activate NF-κB via the canonical pathway." (PMID 38540096, 2024). "Our screening test detects the 10 ERBB2 mutations most frequently observed in breast cancer (p.S310F, p.S310Y, p.L755S, p.D769H, p.D769Y, p.G776V, p.V777L (G>C), p.V777L (G>T), p.V777M, and p.L869R) according to the Catalog of Somatic Mutations in Cancer (COSMIC) database." (PMID 38287892, 2024). "Whether ERBB2-low breast cancer represents a unique subtype is controversial; multiple studies have found associations of ERBB2-low status with response to therapy and prognosis." (PMID 36821125, 2023). "We showed that two PPRHs designed against the ERBB2 gene were able to silence the ERBB2 gene and protein expression and cause a significant decrease in the viability of breast cancer cells in vitro and tumor growth in vivo, either alone or in combination with trastuzumab." (PMID 37108234, 2023). "Interestingly, patients with HER2-positive breast cancer with ERBB2 mutations are less responsive to trastuzumab than ERBB2 wild-type patients." (PMID 38136267, 2023). "Moreover, an analysis of hotspot mutations in the genes PIK3CA, ESR1, AKT1 and ERBB2 frequently present in breast cancer was performed." (PMID 36823365, 2023). "The activated proto-oncogene ErbB2 (also termed neu or HER2) is a leading cause of breast cancer." (PMID 36959802, 2023). "This cohort study assesses whether PIK3CA mutations among patients with ERBB2/HER2-positive early breast cancer are associated with treatment response and outcome, and if these associations vary by hormone receptor status or intrinsic molecular subtype." (PMID 38117494, 2023).
breast cancer (continued). "Breast cancer patients respond well toward immunotherapy in the presence of breast calcifications that are mainly associated with immune dysregulation and Erb-B2 receptor tyrosine kinase 2 (ERBB2) hyperactivation." (PMID 37415164, 2023). "Most nonductal histological tumors were associated with lower proportions of ERBB2-low breast cancer than ductal cancers, including lobular (aOR, 0.73; 95% CI, 0.72-0.74; P < .001), mucinous (aOR, 0.51; 95% CI, 0.49-0.52; P < .001), and metaplastic (aOR, 0.53; 95% CI, 0.50-0.56; P < .001) cancers." (PMID 36821125, 2023). "ERBB2, the protein encoded by ERBB2, plays an important role in breast cancer." (PMID 36857450, 2023). "PIK3CA mutations may be associated with outcomes of patients with ERBB2/HER2-positive early breast cancer (EBC)." (PMID 38117494, 2023). "The mechanisms which contribute to LRIG1 downregulation in breast cancer are not fully understood but are known to include ERBB2-mediated repression and loss of gene copy number, which conveys persistent risk of relapse in patients typically considered low-risk." (PMID 35440669, 2022). "The datasets “Phenotypes” and “IlluminaHiSeq Gene Expression RNAseq” were downloaded in order to identify breast cancer patients with mutations affecting BRCA1 or BRCA2 or amplification affecting ErbB2 and the expression data of 20,530 different genes, respectively." (PMID 35740092, 2022). "Based on the CNV data, several special CNV regions were identified, including gain peaks containing known breast cancer driver genes such as ERBB2 and NOTCH2, as well as the loss peaks containing some known tumor suppressor genes such as PRDM16 and STK11 (CNV focal peak gene annotation)." (PMID 35013309, 2022). "Here, we examined whether dapagliflozin would slow tumor growth in lean MMTV-PyMT mice, a murine breast cancer model driven by the polyoma virus middle T antigen and commonly expressing an Erbb2 mutation." (PMID 35595952, 2022). "Thus, it was reasonable to suggest that the software computed up-2 cutoff, which separated class 2 and higher from lower classes, was a diagnostic cutoff point associated with ERBB2/HER2 overexpression in the subset of breast cancers." (PMID 36335194, 2022). "Despite ERBB2 being a well-known oncogene and regarded as a crucial diagnostic/prognostic biomarker and therapeutic target in multiple tumors, such as breast cancer, the exact function of ERBB2 in tumors remains largely unknown." (PMID 36437939, 2022). "To examine the role of BLNK in the regulation of anoikis of ErbB2-overproducing breast cancer cells by a complementary approach, we generated a variant of MCF-ErbB2 cells MCF-ErbB2-BLNK in which exogenous BLNK expression is controlled by the doxycycline-inducible promoter." (PMID 35933456, 2022). "The TNFAIP1/POLDIP2 CSAGA is a clinically relevant transcriptional structural-functional gene module linked to erb-b2 receptor tyrosine kinase 2 (ERBB2) amplicon core gene expression in breast cancer and connected with amplification of the genomic region on 17q11.2." (PMID 36425112, 2022). "Thus, HSP90 is a promising target for anti-tumor therapy, because one of the most well-defined HSP90 client proteins in breast cancer is the ERBB2/Her2." (PMID 35890234, 2022). "Results from phase I studies, carried out in patients with breast cancer, showed that targeting anticancer agents via antibodies to ErbB2 might cause toxicities due to its expression in normal cells." (PMID 35744957, 2022). "It has been shown that ERBB2 activation leads to increased autophagy in breast cancer cells, but the underlying mechanisms remains unclear." (PMID 33801244, 2021).
breast cancer (continued). "Moreover, mice lacking CCND1 gene, which encodes the cyclin D1 protein, were unable to develop mammary tumors dependent upon ErbB2 or RAS." (PMID 33805800, 2021). "Overexpression of FOXM1 and ERBB2 lead to genomic instability and uncontrolled cell division and malignancy, which are associated with poor prognosis in various cancerous lesions including breast cancers." (PMID 34565361, 2021). "Moreover, the mutation of receptor ERBB2 frequently appeared in breast cancer and participated in the migration of cancer cells." (PMID 33802957, 2021). "It is well-known that ERBB2 expression can cause chemo- and radio-resistance in breast cancer." (PMID 33801244, 2021). "ERBB2 is known to be associated with HER2 subtype and has been well studied in breast cancer." (PMID 34744522, 2021). "At the individual gene level and compared to controls, ATF3-induced mammary tumors exhibited reduced expression of Rb1, Esr1, and Pgr, and increased expression of Erbb2, Egfr, and the genes encoding keratins 5, 6, and 17, which is similar to basal-like human breast cancer tumors." (PMID 33652981, 2021). "Indeed, loss of CdGAP in ErbB2-expressing mouse mammary tumor cells and in human breast cancer MDA-MB-231 cells resulted in a decrease of SNAIL1 and ZEB2 concomitantly with an increase of E-cadherin and reinstatement of cellular adherens junctions." (PMID 34493786, 2021). "The new insights into mechanisms that control the surface expression of overexpressed ErbB2 identified here support the potential of exploring combined treatment with Trastuzumab and ER stress-inducing agents in ErbB2-overexpressing breast cancers with loss of CHIP expression." (PMID 34439093, 2021). "Indeed, ERBB2 gene amplification is observed in 20–25% of breast cancers and causes the overexpression of the HER2 protein." (PMID 34664433, 2021). "To investigate a possible role for ATM-dependent PTEN phosphorylation in breast cancer, we bred the Pten398A allele on the background of mice expressing the inactivated neu (Erbb2) fusion gene under the transcriptional control of the mouse mammary tumor virus (MMTV) promoter/enhancer (MMTVneu)." (PMID 34059798, 2021). "More studies are required to pinpoint whether the expression of ERBB2 plays a driver or passenger role in the BRCA1-deficient mouse mammary tumors." (PMID 34815798, 2021). "Indeed, about 15–20% of breast cancers (BCs) harbor amplifications of the ERBB2 oncogene, which encodes for HER2, and this alteration leads to a more aggressive behavior of disease compared to HER2-negative (HER2–) cases." (PMID 36046143, 2021). "The demonstration that Ppm1d-deficient mice significantly delayed the formation of ERBB2-induced mammary tumors and that Ppm1d-null embryonic mouse fibroblasts were resistant to transformation by RAS, ERBB2, and c-MYC encouraged us to establish a genetically modified mouse model overexpressing WIP1." (PMID 34771656, 2021). "ERBB2 copy number amplification is an essential mutation in breast cancer." (PMID 33893247, 2021). "Recent research showed that ErbB2+ breast cancers express higher levels of gene-encoding proteins in the ERAD pathway, potentially as a strategy to cope with ER stress caused by higher ER biosynthetic load from high abundance of ErbB2 and proteins in downstream pathways." (PMID 34439093, 2021). "Additionally, we identified a significant association of genes involved in treatment response in breast cancer with genes producing splicing-derived neoepitopes (ERBB2, ESR1, TIMP1, ABCC3) or potentially depleted self-epitopes (AKT1, CCNE1, RET, TFF3)." (PMID 34529669, 2021). "This supports that autophagy promotion by upregulation of ATG12 and MAP1LC3B might cause treatment resistance of ERBB2-positive breast cancer, leading to a worse outcome for breast cancer patients." (PMID 33801244, 2021).
breast cancer (continued). "Consequently, ECD KD in ErbB2+ breast cancer cells led to decreases in ErbB2 mRNA levels and its stability, which was associated with impairment of oncogenic traits." (PMID 33941617, 2021). "We tested these hypotheses by mining a combined dataset of the three largest primary breast cancer series with data on tumor ERBB2 and ERBB3 mutational status, gene expression, clinicopathological features, and patient survival outcomes." (PMID 32782013, 2020). "In contrast, MMTV-erbB2 transgenic mice have a defined genetic background and are a well-established clinically relevant model for erbB2-mediated carcinogenesis, which is also often used to test environmental factor-modulated mammary tumor risk." (PMID 32353937, 2020). "Furthermore, studies have shown that the miRNA-145/143 cluster targets the 3′-UTR of the ERBB2 gene, which has been linked with breast cancer multidrug resistance in a subtype dependent manner." (PMID 31979312, 2020). "ERBB2 L869R mutation was reported to contributed to Trastuzumab resistance in breast cancer." (PMID 33377634, 2020). "In addition to its modulation of the OXPHOS to glycolysis switch, PGC-1α is also associated with glutamine metabolism in ERBB2+ breast cancer cells; PGC-1α activity increased glutamine uptake and metabolism enzymes." (PMID 33266219, 2020). "Furthermore, a previous study revealed that CDK4 and MDM2 mutations occurred in melanomas and liposarcoma, while ERBB2 mutations occurred in breast cancer, EGFR mutations occurred in astrocytoma, and MYCN mutations occurred in neuroblastoma." (PMID 32711494, 2020). "Recently, FDA approved pertuzumab in combination with trastuzumab, for patients with ERBB2-positive breast cancer with high-risk recurrence, and pertuzumab treatment alone showed significant improvement of invasive disease-free survival in breast cancer patients." (PMID 32708604, 2020). "In fact, the only level 1 annotated variant in breast cancer is ERBB2 amplification." (PMID 30736836, 2019). "Moreover, the decreased expression of miR-34a is inversely correlated with the increased V-Erb-B2 avian erythroblastic leukemia viral oncogene homolog 2 (ErbB2) levels in breast cancer associated with the promotion of cell proliferation." (PMID 31766744, 2019). "Normally, 35% of breast cancer is Erb-B2 Receptor Tyrosine Kinase 2 (ERBB2)-positive that predisposes to poor prognosis and relapse, while ethanol drinking leads to invasion of their ERBB2 positive cells triggering the phosphorylation status of mitogen-activated protein kinase." (PMID 30611309, 2019). "To determine whether the metabolic phenotypes of chronically c-Src-deficient ErbB2+ tumor cells are reproduced by acute c-Src loss, we expressed Cre recombinase using adenoviral vectors in ErbB2+ breast cancer cells with homozygous conditional Src alleles." (PMID 31263101, 2019). "ErbB2 is an oncogene receptor tyrosine kinase linked to breast cancer." (PMID 30917575, 2019). "For example, Cluster C2 contains p140Cap and the tyrosine kinases Src and Erbb2, reinforcing the concept that p140Cap can associate and regulated tyrosine kinases, which play key roles in breast cancer transformation and progression." (PMID 31681758, 2019). "In breast cancer, ERBB2 over-expression is highly associated with tumorigenesis." (PMID 30870514, 2019). "In addition, the fourth and fifth are ENSP00000269571 and ENSP00000275493, which are encoded by Erbb2 and Egfr, respectively, are all highly linked to breast cancer." (PMID 31818267, 2019). "Interestingly, high levels of CD73 have been associated with resistance to HER2/ErbB2 inhibitor therapy in preclinical breast cancer models and poor clinical outcome of breast cancer patients under Trastuzumab therapy." (PMID 31623231, 2019).
breast cancer (continued). "Human epidermal growth factor receptor 2 (ERBB2 or HER2) amplification/overexpression is associated with a particularly aggressive molecular subtype of breast cancer (BC), characterized by a poor prognosis, increased metastatic potential, and disease recurrence." (PMID 31261614, 2019). "Recently, we have found that ErbB2 and nucleolin physically interact in cells, and that this interaction leads to activation of ErbB2 and its downstream signaling, which culminates in increased cell growth and tumorigenicity, and in increased disease and mortality risk in breast cancer patients." (PMID 29352243, 2018). "ErbB2-positive breast cancer is associated with higher mortality rates and multi-drug resistance." (PMID 29352243, 2018). "Recently, we have shown that ErbB2 interacts with the nuclear-cytoplasmic shuttling protein nucleolin, an interaction which enhances cell transformation in vitro, and increases mortality risk and disease progression rate in human breast cancer patients." (PMID 29352243, 2018). "While both the mouse and human tumors show strong expression of mature luminal cell differentiation signatures and activation of several pathways, mouse microacinar tumors also show activation of Erbb2 signaling, which is traditionally associated with the Her-2 enriched subtype of breast cancer." (PMID 29346386, 2018). "Moreover, the expression of both FOXM1 and UBE2C in breast cancer has already been associated with ErbB2 pathway." (PMID 29596365, 2018). "In particular, ganetespib offers a promising chemotherapeutic strategy for refractory ErbB2+ breast cancers, even in the presence of mutations in the extracellular and tyrosine kinase domains of ErbB2, which are associated with primary resistance to ErbB2-targeting therapeutics." (PMID 29717218, 2018). "Amplifications of RANBP9 occur in breast cancer in vivo and are associated with increased gene expression, although amplifications are less common than for ERBB2, suggesting other mechanisms more typically driving its overexpression." (PMID 30205839, 2018). "The extent to which these processes are linked to ERBB2 amplification in HER2+ breast cancer is largely unknown." (PMID 30005627, 2018). "Moreover, cyclohexamide noticeably enhanced selumetinib-induced ErbB2 protein loss in detached breast cancer cells." (PMID 29285258, 2017). "Previously we found that the estrogen receptor (ER) related factor ERRF regulates cell proliferation and tumor growth, and its expression is positively associated with ER status and better survival but inversely associated with ERBB2 (also named HER2) status in breast cancer." (PMID 28415602, 2017). "In search for physiologically relevant circumstances under which this scenario could take place we reasoned that ErbB2 loss represents an established mechanism of breast cancer resistance to treatment with a therapeutic anti-ErbB2 antibody trastuzumab." (PMID 29285258, 2017). "And many researches demonstrated that ERBB2 was associated with chemoresistance of breast cancer." (PMID 29163776, 2017). "Taken together, our data provide evidence for buformin as an effective anti-cancer drug, especially in patients at a high risk for developing erbB-2-overexpressing breast cancers, and may ultimately have a significant impact on breast cancer prevention." (PMID 28193239, 2017). "On the basis of the association between p140Cap status and reduced risk of distant metastasis in ERBB2 breast cancer patients, and on the down-regulation of the EMT transcription program, we addressed the putative protective role of p140Cap against the metastatic risk." (PMID 28300085, 2017).